ATP6V1C1 (ATPase H+ transporting V1 subunit C1)
Diseases named in the same sentence as ATP6V1C1 in open-access papers (continued):
Sharing a sentence is not in itself a finding about the gene and the disease.
periodontal disease (1 paper, 2015). "In our current study, we found that knockdown of the targeted subunit (Atp6v1c1) of Atp6i by an AAV vector can inhibit inflammation and reduce periodontal disease progression significantly." (PMID 26274612, 2015).
ZIKV infection (1 paper, 2022). "ZIKV infection significantly upregulated genes related to lysosomal biosynthesis, including LAMP1 and CLCN7 (lysosomal transmembrane proteins); CSTB and CSTD (lysosomal hydrolases); and ATP6V1C1 and ATP6V0D1 (v-ATPase proteins)." (PMID 36405969, 2022).
tumor (9 papers, 2014 to 2025). "These two populations expressed genes Cxcl3, Ccl3, Ccl4, Atp6v1c1, Atp6v0d2, which have been associated with a tumor promoting phenotype." (PMID 38265267, 2024). "Collectively, high ATP6V1C1 expression correlates with poor tumor prognosis, and ATP6V1C1 knockout sensitized cells to chemotherapy." (PMID 40384877, 2025). "Kaplan-Meier (KM) analysis reveals a significant deterioration in the prognosis of patients with high ATP6V1C1 expression, indicated by an elevated hazard ratio (HR) in 11 tumor types." (PMID 40384877, 2025). "We assessed atp6v1c1 expression across 33 tumor types and corresponding normal (or adjacent cancer) tissues using TCGA and GTEx datasets." (PMID 40384877, 2025). "We have shown that ATP6v1c1 has effects on tumor growth and metastasis with ATP6v1c1 knockdown reducing tumor growth and metastasis in vivo." (PMID 28504970, 2017). "ATP6v1c1 knockdown also significantly reduces tumor stimulated bone resorption through osteoclastogenesis at the bone and metastasis in vivo, as well as V-ATPase activity, proliferation, and mTORC1 activation in vitro." (PMID 28504970, 2017). "H&E staining confirmed the Micro-CT results and further showed that tumor growth in the bone was decreased in the ATP6v1c1 knockdown groups." (PMID 28504970, 2017). "In addition, ATP6V1C1 was also reported to display resistance to cytotoxic drugs, and therefore could be a potential therapeutic target for chemo-resistant tumor treatment." (PMID 30355311, 2018). "Thus, we formulated the hypothesis regarding the involvement of ATP6V1C1 in tumor progression." (PMID 40384877, 2025). "In prior investigation, we observed the targeting of ATP6V1C1 by VAM and demonstrated its anti-tumor efficiency." (PMID 40384877, 2025). "Therefore, in this paper, we look into the role of ATP6v1c1 in tumor growth, and metastasis, as well as its role in mTOR signaling in both human and murine cancer cell lines to determine whether its knockdown can inhibit tumor growth." (PMID 28504970, 2017).
cancer (8 papers, 2014 to 2025). A tumor composed of atypical neoplastic, often pleomorphic cells that invade other tissues. "Overall, this work presents an efficient strategy for target identification, demonstrating its successful application in identifying ATP6V1C1 as a promising target for cancer treatment." (PMID 40384877, 2025). "Here, the TCGA dataset reveals a correlation between elevated ATP6V1C1 expression and the advancement of malignant tumors." (PMID 40384877, 2025). "ATP6V1C1 controls tumor growth and bone metastasis, and the silencing of the gene suggests treatment and prevention strategies against cancer." (PMID 32992741, 2020). "As a result, we identified eight common mutated genes (EBAG9, MTDH, ATP6V1C1, OPA1, ATCL6A, BCL6, SENP5, KRAS) in the three different cancer types and used them as cross-cancer biomarkers to perform an integrative network analysis." (PMID 29459674, 2018). "To generalize the effects of ATP6v1c1 knockdown on proliferation and mTORC1 activation we used human cancer cell lines - MCF-7, MDA-MB-231, and MDA-MB-435s." (PMID 28504970, 2017). "To knockdown ATP6V1C1 in these human cancer cells, we used lentiviruses expressing different shRNAs to target human C1, and lentiviruses expressing a scramble shRNA (as a control) to infect the human cancer cell line MDA-MB-435s in order to select the most efficient C1 targeting shRNA." (PMID 28504970, 2017). "By directly binding to ATP6V1C1, VAM inhibits V-ATPase catalytic activity and lysosomal acidification, ultimately disrupting the autophagic-lysosomal pathway essential for cancer cell survival." (PMID 40384877, 2025). "ATP6V1C1 knockdown reduced cell proliferation and impaired mTORC1 pathway activation in cancer cells but not in the untransformed cell line C3H10T1/2." (PMID 28504970, 2017).
ATP6V1C1 also shares sentences with these, for which no sentence is quoted: oral cancer (3 papers); atherosclerosis (1); cognitive decline (1); dementia (1); glioblastoma (1); infection (1); neurodegenerative disease (1); osteosarcoma (1); pancreatic adenocarcinoma (1); peripheral T cell lymphoma (1); renal cell carcinoma (1); rheumatoid arthritis (1); Sepsis (1); type 2 diabetes (1); viral myocarditis (1).